BCL2 (BCL2 apoptosis regulator)
Diseases named in the same sentence as BCL2 in open-access papers (continued):
Sharing a sentence is not in itself a finding about the gene and the disease.
esophageal cancer (continued). "This suggested that metformin induced apoptosis of esophageal carcinoma cells partly regulated by the Stat3/Bcl-2 pathway, which may have little function on normal esophageal epithelial cells." (PMID 32258099, 2020). "Our findings, together with those of other studies, indicated that sulforaphene could repress MSK2, and CREB, Bcl-2, down-regulate the C-cadherin expression and thereby induced apoptosis and inhibited invasion in esophageal cancer cells." (PMID 31889894, 2019). "Interestingly, we found that EDHB treatment not only led to apoptosis but also autophagic cell death via the up-regulation of BCL-2/EIB-19K-interacting protein 3 (BNIP3) and Beclin and the down-regulation of BCL-2 in the esophageal cancer KYSE 170 cells." (PMID 25232961, 2014). "Through silencing Bcl-2, miR-130a-3p could sensitize esophageal cancer cells to DDP." (PMID 34881242, 2021). "In contrast, in the present study, we observed a significant decrease in the level of Bcl-2 accompanied by increased levels of Bax, caspase-3, and caspase-9, indicating that pristimerin is able to trigger intrinsic apoptosis thereby inducing esophageal cancer cell death." (PMID 31218209, 2019). "In conclusion, our results demonstrate that SKF96365 inhibits tumor growth by inhibiting TRPC1 in esophageal cancer cells and inducing apoptosis (PARP, caspase-9, and BCL-2) and autophagy (LC3-A/B)." (PMID 39165489, 2024). "In summary, SKF96365 induces apoptosis (PARP, caspase-9, and BCL-2) and autophagy (LC3-A/B) by inhibiting TRPC1 in esophageal cancer cells, thereby inhibiting tumor growth." (PMID 39165489, 2024). "In oesophageal cancer cells, GPR176 silencing was shown to ameliorate proliferation and induce apoptosis by either inactivating PI3K/Akt/mTOR or decreasing Bcl-2/Bax." (PMID 37584712, 2023). "Hypomethylated PLCE1 stimulates esophageal carcinoma angiogenesis and proliferation by activating the PI-PLC epsilon-NF-B signaling pathway and VEGF-C/Bcl-2 expression." (PMID 35765945, 2022). "Furthermore, KYSE450, KYSE510, and KYSE30 esophageal cancer cells treated with the compound exhibited substantial up-regulation of apoptosis-associated proteins, including cleaved-PARP, cleaved caspase 3 and pro-apoptotic Bax whereas anti-apoptotic Bcl-2 expression was decreased." (PMID 28881819, 2017). "Our data also showed the up-regulation of proteins such as HSP70, BCL-2 and BIRC5 in the cisplatin-treated esophageal cancer cells, indicating an increase in the anti-apoptotic molecular pattern." (PMID 24959694, 2014). "We have designed a novel and versatile self-assembling nanoparticle (NP) platform on a multifunctional carboxymethyl chitosan base to simultaneously deliver Adriamycin, and siRNAs targeting MVP and BCL2 (CEAMB NPs), thus reducing drug efflux and promoting apoptosis of esophageal cancer cells." (PMID 35346194, 2022). "Bax, cleaved caspase-3, cleaved caspase-9, cytochrome C and cleaved PARP levels were increased after treatment with Rk3, whereas Bad and Bcl-2 levels were reduced in a dose-dependent manner in both Eca109 and KYSE150 cells, indicating that Rk3 activated apoptosis in esophageal cancer cells." (PMID 31091245, 2019). "Although apoptotic biomarkers were not assessed in our study, the downregulation of Bcl-2 and the increase of BAX Might explain the results of our research, which indicates that DPMSC-CM caused the death of esophageal cancer cells by increasing apoptotic markers." (PMID 41585335, 2026).
oral cancer (58 papers, 2007 to 2025). "In the oral cancer cell line KB-1, T. terrestris can cause apoptosis by lowering Bcl-2 protein levels, raising caspase-3 activity, and degrading DNA." (PMID 39262564, 2024). "Another virus involved in malignant transformation is EBV, which is strongly associated with oral carcinoma progression by the action of the LMP-1 EBV-encoded oncogene when the human epithelial cells co-express Bcl-2." (PMID 39337467, 2024). "Meanwhile CA+AA genotypes in BCL2 rs2279115 were related with a higher risk of developing oral carcinoma (p = 0.010, OR = 2.753 (1.273–5.952)) in a dominant model." (PMID 30959967, 2019). "Oral cancer is linked with apoptotic proteins such as Bcl-xl, Bcl-2 and Mcl-1." (PMID 32994681, 2020). "The loss of Bcl-2 expression is related to the increase of oral carcinoma proliferation activity." (PMID 26494988, 2015). "Although several clinical studies have shown that Bcl-2 expression is associated with neck lymph node metastasis and poor prognosis in oral cancer, the functional roles of Bcl-2 in OTSCC and whether it is involved in the resistance of OTSCC to chemotherapy are not well understood." (PMID 27722045, 2016). "Furthermore, Bcl-2 and Bcl-xL, anti-apoptotic factors associated with the intrinsic mitochondrial-dependent apoptotic signaling pathway, were downregulated significantly by berberine treatment in the KB oral cancer cells." (PMID 25634589, 2015). "The genes BAD, BAX, caspase-3, and Bcl-2 are thought to be markers specific to KB1 oral cancer cells." (PMID 39156270, 2024). "In oral cancer, dysregulation of apoptosis-related genes such as BCL2, which inhibits apoptosis, and BAX, which promotes apoptosis, can disrupt the delicate balance between cell proliferation and cell death, leading to uncontrolled tumor growth." (PMID 38907185, 2024). "In oral cancer cells, we found that treatment with naringin markedly reduced Bcl-2 and increased the expression of the anti-apoptotic genes BAD, BAX, and caspase-3." (PMID 39156270, 2024). "Regarding anticancer mechanisms of purple bamboo salt on oral cancer, induction of apoptosis by increasing the number of apoptotic bodies and regulating the expression levels of the apoptosis-related Bax and Bcl-2 mRNA and proteins has been suggested." (PMID 35069740, 2022). "Immunohistochemical staining by monoclonal antibody to Ki-67 and Bcl-2 in the study group showed lower expression at all stages of oral cancer development compared with their expression in the control group." (PMID 35865422, 2022). "As an anti-apoptotic factor, Bcl-2 protein expression in oral cancers is well documented, although large variability exists with inconsistent historical reports of patient sample Bcl-2 expression in less than 10% of oral tumours to greater than 50%." (PMID 35163485, 2022). "BCL2 is targeted directly by miR-21 a transcript having the highest expression level in oral cancer, which is in accordance with the low expression level of BCL2." (PMID 35723379, 2022). "The result was in agreement with Yuan’s finding that EGCG treatment resulted in alteration of AKT/STAT3 signaling and downregulation of Bcl-2 in oral-cancer CAR cells." (PMID 33747527, 2021). "The effect of PAC of caspase signaling for oral cancer cell apoptosis was confirmed by Western blotting showing that PAC at 5 μM strongly decreases Bcl-2 expression and increases that of pro-apoptotic Bax and cytochrome C as well as allows cleavage of PARP-1." (PMID 34083581, 2021). "Recently, our team demonstrated that TW-37 functions as a potential apoptosis-inducing agent for the treatment of oral cancer by reducing heme oxygenase-1 and Bcl-2." (PMID 32863764, 2020).
oral cancer (continued). "Bcl-2 family proteins Bcl-2 and Bcl-xL are resistant to multiple chemotherapeutic agents in a variety of cell lines, and it was reported that NCTD downregulated the expression of Bcl-2 and Bcl-xL in oral cancer cells." (PMID 32514288, 2020). "We provide strong evidence that co-culture with MSCs results in increased expression of bcl-2 in oral cancer cells, and these events appear to be mediated via activation of AKT at T308 and S473." (PMID 32411595, 2020). "In this study, both LF-CQPC08 and LDSB effectively inhibited the expression of Bcl-2 and Bcl-xL and increased the expression of Bax, thereby exerting their inhibitory effects on the oral cancer in the mice." (PMID 30861992, 2019). "For oral cancers, BCL2 were proved to be important in cancer progression and chemoradiation resistance." (PMID 31744202, 2019). "Regarding their role in the forms of OSCC, an increase in the levels of Bcl-2 and Bcl-X expression was observed, both in dysplastic oral lesions and in oral cancer." (PMID 31019584, 2019). "Inhibition of BCL2 in oral cancer cells inhibited proliferation and induced apoptosis, and also augmented the inhibitory effects of cisplatin in vitro and in vivo." (PMID 31744202, 2019). "In oral cancer, Bcl-2 and Bcl-xL expression plays a role in promoting tumor growth, and Bax expression plays a role in suppressing the cancer." (PMID 30861992, 2019). "In some studies on human oral cancer biopsies, Bcl-2 levels have been reported to be increased compared to normal oral mucosa." (PMID 31687322, 2019). "In this study, treatment with ROS scavenger NAC reduced the levels of p-Akt, cyclin D1, PCNA, and Bcl-2 and increased the expression of Bax in oral cancer cells." (PMID 29725496, 2018). "At the same time, berberine decreased the expression of mitochondrial-dependent anti-apoptotic factors such as Bcl-2 (molecular weight 26 kDa) and Bcl-xL (molecular weight 16 kDa) in the KB oral cancer cells." (PMID 25634589, 2015). "Using Co-immunoprecipitation, we demonstrated that 14-3-3ζ protein binds to NFκB, β-catenin and Bcl-2, suggesting its involvement in cellular signaling, leading to proliferation of oral cancer cells." (PMID 17764575, 2007). "Cinnamomum cassia extract (CCE) could suppress human oral cancer cell growth via caspase‐3 cleavage, Bcl‐2 reduction, and increasing autophagic markers, including LC3A, autophagy‐related protein 14, Rubicon and p62 in vivo and in vitro." (PMID 33980998, 2022). "We can suggest that autophagy may be related to the apoptosis induction by anethole treatment of oral cancer cells by increasing the Bax/Bcl-2 ratio and activating the subsequent caspases." (PMID 34158560, 2021). "Also, our results demonstrate that PAC strongly induces oral cancer cell apoptosis mediated via the mitochondrial pathway by increasing the Bax/Bcl-2 protein expression ratios, activating caspase-3/9 and cleaving PARP-1." (PMID 34083581, 2021). "Bcl‐2 and survivin are upregulated during proliferation of oral cancer." (PMID 33898183, 2021). "As TW-37 is a potent inhibitor of anti-apoptotic Bcl-2 family proteins, such as Bcl-2, Bcl-xL, and Mcl-1, we assessed whether TW-37-induced apoptosis in human oral cancer cell lines could regulate these proteins." (PMID 32863764, 2020). "Increased Bcl-2 and decreased Bax are frequently observed in oral cancer." (PMID 29725496, 2018). "Hence in the present study, we evaluated the efficacy of a BH3-mimetic pan-BCL-2 inhibitor Obatoclax against human oral cancer cell lines and also elucidated the mechanism of its action." (PMID 28947954, 2017).
oral cancer (continued). "Hence, we investigated the efficacy and mechanism of action of Obatoclax, a BH3 mimetic pan BCL-2 inhibitor in human oral cancer cell lines." (PMID 28947954, 2017). "In this study, Bcl-2 and Bcl-xL expression decreased in DA-treated oral cancer cells." (PMID 26356821, 2015). "Therefore, it would be reasonable to postulate that Bcl-xL and Bcl-2 contribute to ABT-737 resistance in human oral cancer." (PMID 26447615, 2015). "Fourth, DA inhibits Bcl-2, Bcl-xL and Mcl-1 expression in oral cancer cells." (PMID 26356821, 2015). "In this study, Bcl-2, Bcl-xL and Mcl-1 expression levels decreased in DA-treated oral cancer cells." (PMID 26356821, 2015). "In this context, we demonstrated the binding of 14-3-3ζ with Bcl-2 in oral cancer cells and propose that the interaction of 14-3-3ζ with Bcl-2 may result in its sequestration and consequent abrogation of apoptosis." (PMID 17764575, 2007). "Likewise, costunolide induced mitochondria-mediated apoptosis by upregulation of Bax, downregulation of Bcl-2, and activation of caspase-3 and poly ADP-ribose polymerase via ROS production and loss of mitochondrial membrane potential in oral cancer Eca-109 cells." (PMID 31208018, 2019). "In summary, this research emphasizes the potential of naringin as a cytotoxic and pro-apoptotic phytochemical that modulates the expression of Bcl-2, TGF-β, SMAD2, TNFα, NFκB, BAD, BAX, and caspase-3 genes, ultimately aiding the treatment of oral cancer." (PMID 39156270, 2024). "Overall, this study highlights the promising role of naringin as a pro-apoptotic and cytotoxic phytochemical regulating the gene expression of Bcl-2, TGF-β, SMAD2, TNFα, NFκB, BAD, BAX, and caspase-3, thereby treating oral cancer." (PMID 39156270, 2024). "In oral cancer, the silence of AKT1 and AKT2 inhibited the expression of COX-2, cyclinD1, and Bcl-2, which in turn inhibited cell survival." (PMID 36734243, 2023). "In human oral cancer OC2 cells in vitro, BITC inhibits growth and triggers apoptosis by reducing Mcl-1 and Bcl-2 expression and increased PARP cleavage." (PMID 30970087, 2019). "In this study, we have developed a novel siRNA-based therapeutic strategy targeting BCL2 and BIRC5 for oral cancer." (PMID 31744202, 2019). "Here, polyethyleneimine (PEI)-modified magnetic Fe3O4 nanoparticles were prepared for the delivery of therapeutic siRNAs targeting B-cell lymphoma-2 (BCL2) and Baculoviral IAP repeat-containing 5 (BIRC5) into Ca9-22 oral cancer cells." (PMID 31744202, 2019). "In this study, we found that melatonin impaired the proliferation and apoptosis resistance of oral cancer cells by inactivating ROS-dependent Akt signaling, involving in downregulation of cyclin D1, PCNA, and Bcl-2 and upregulation of Bax." (PMID 29725496, 2018). "In oral cancer, ATX apparently decreased the phosphorylation of AKT, followed by a reduction of Bcl-2, p-Bad and survivin, a concomitant increase of Bax, Bad and cleaved PARP, resulting in significant apoptosis." (PMID 26184238, 2015).
oral cancer (continued). "Moreover, the expression of cyclin-D1, Bcl-2, and MMP-9 were upregulated and caspase-9 was downregulated, which are the key molecules involved in oral cancer cell proliferation, survival, invasion, and migration." (PMID 29996471, 2018). "Moreover, cyclin-D1, Bcl-2, and matrix metalloproteinase-9 (MMP-9) were upregulated, and caspase-9 was downregulated, suggesting that silencing of NGAL increases oral cancer cell proliferation, survival, and migration." (PMID 29996471, 2018). "Interestingly, we also found that Bcl-xL and Bcl-2 are not targeted by ABT-737 in either human oral cancer cell line." (PMID 26447615, 2015). "In this study, we prepared Fe3O4 nanoparticles and design siRNAs targeting BCL2 and BIRC5, aiming to explore the efficient delivery of therapeutic siRNA into oral cancer cells by Fe3O4 nanoparticles, which might provide a novel strategy for the future therapy of oral cancer." (PMID 31744202, 2019).